IL10 (interleukin 10)
Diseases named in the same sentence as IL10 in open-access papers (continued):
Sharing a sentence is not in itself a finding about the gene and the disease.
schistosomiasis (87 papers, 2007 to 2026). An infectious disease caused by parasitic trematodes of the genus Schistosoma that colonize human blood vessels and release eggs that can cause granulomatous reactions leading to acute (swimmer's itch or acute schistosomiasis syndrome) or chronic disease. "In contrast, IL-10 plays a regulatory role in schistosomiasis, preventing the development of excessive pathologies caused by both Th1 and Th2 responses." (PMID 37296126, 2023). "Specifically, TH2-associated cytokines IL-4, IL-5, IL-10, and IL-13 from splenic cell preparations appeared elevated in offspring exposed to treated maternal schistosomiasis." (PMID 35833137, 2022). "Some factors, including IL-10, Tregs, B cells, antibodies, T cell anergy, macrophages, and microRNAs, are related to the pathogenic immune response in schistosomiasis." (PMID 33628844, 2021). "Given the importance of IL-10 and TNF-α in schistosomiasis, this cross-sectional study was designed to determine possible links between single nucleotide polymorphisms (SNPs) in promoter regions of IL-10 and TNF-α genes and susceptibility to schistosomiasis." (PMID 34485462, 2020). "Treatment of schistosomiasis is also associated with changes in circulating cytokine concentrations, such as a decline in circulating IL-10." (PMID 30763405, 2019). "IL-10 has been implicated as a key immunoregulatory factor driving host resistance to schistosomiasis." (PMID 30619289, 2018). "Among 58 participants, 33 (57%) had schistosomiasis, which was associated with elevated levels of interleukin (IL)-10 (0.32 vs. 0.19 pg/ml; p = 0.038) and a trend toward increased tumour necrosis factor (TNF) (1.73 vs. 1.42 pg/ml; p = 0.081)." (PMID 30453907, 2018). "Interleukin-10 has previously been correlated with control of pathogenesis, reduction of morbidity and prolonged survival in human schistosomiasis, but has also been linked to a decreased resistance to reinfection." (PMID 29692308, 2018). "This negative correlation was reproduced in murine model and had been associated to some schistosomiasis induced features such as IL-10 and TGF-β production and increased numbers of regulatory T and B cells." (PMID 27454771, 2016). "Various cells have been implicated in IL-10 production but the distinct cellular sources of this cytokine remain poorly defined in both human and experimental schistosomiasis." (PMID 18045464, 2007). "Additionally, a suppressed immunological status characterized by the growth of Treg cells and IL‐10 has been linked to maternal schistosomiasis." (PMID 39560407, 2024). "Taken together, these observations support the hypothesis that the association between IL-10 levels and schistosomiasis in our study is due to higher IL-10 levels predisposing to infection and lower levels conferring protection." (PMID 34007813, 2021). "Higher TNF-α and lower IL-10 levels were negatively associated with infection and may confer protection against schistosomiasis." (PMID 34007813, 2021). "While many researchers are focused on the Tregs-associated suppression and the powerful force of IL-10, successful immunotherapies will only be developed for schistosomiasis if we have a broader view and deeper understanding of the mechanism of T-cell-mediated liver immunopathology." (PMID 32132991, 2020). "Controlled studies may also highlight the link between IL-10 production levels to susceptibility to schistosomiasis." (PMID 34485462, 2020). "With regard to helminths, we have previously shown that Schistosoma mansoni, the causative agent of Schistosomiasis and also a skin-penetrating parasite, induces a similar early dermal induction of immune regulation, characterized by PD-L1 expressing and IL-10 producing dermal APCs." (PMID 32898164, 2020). "The main underlying cause may be the strong Th2-response induced by schistosomiasis and the high expression of interleukin-10 (IL-10) by Th2 cells." (PMID 23717704, 2013).
schistosomiasis (continued). "Our study suggests that schistosomiasis coinfection favours anti-malarial protective antibody responses, which could be associated with the regulation of IL-10 and IFN-γ production and seems to be antigen-dependent." (PMID 20856680, 2010). "In the course of schistosomiasis, the Th1 response is modulated by the production of interleukin-10 (IL-10) and later shifts toward an antigen-driven Th2-type response." (PMID 41479896, 2025). "IL-10 levels followed a similar trend, with significantly higher values in schistosomiasis-infected individuals (median: 27.41 pg/mL, IQR: 19.36–64.29) than in uninfected individuals (median: 32.51 pg/mL, IQR: 20.34–51.51), p < 0.0001." (PMID 40526709, 2025). "Schistosomiasis diagnosis was confirmed through urine microscopy using filtration methods, while full blood count and cytokine (IL-4, IL-10) analysis were performed on blood samples." (PMID 40526709, 2025). "In the pathological context of schistosomiasis, the upregulation of IL-10 signaling pathway exerts dual protective effects." (PMID 41154658, 2025). "IL-10 was designated as the central immunomodulatory regulator in the pathogenesis of schistosomiasis." (PMID 39404406, 2024). "IL-10 levels were elevated in human African trypanosomiasis, hookworm and soil-transmitted helminths, and schistosomiasis coinfections." (PMID 36716305, 2023). "Cytokines such as TNF-α, IL-1β, IL-6, IL-4, and IL-10, among others, show increased serum levels during schistosomiasis, reflecting the polarization and complexity between Th1 and Th2 immune responses." (PMID 38239348, 2023). "Blocking PGE2 receptors (EP2 and EP4) in the early schistosomiasis would limit IL-4 and IL-10 production." (PMID 35396684, 2022). "On the other hand, IL-10 has a regulatory role in schistosomiasis, preventing the development of excessive pathologies mediated by both Th1 and Th2 responses." (PMID 33815321, 2021). "This was shown in mice immunized with schistosome egg antigens (SEA) and complete Freunds adjuvant, and again in mice that lack both IL-10 and IL-4, which reached 100% mortality upon infection with schistosomiasis." (PMID 33304354, 2020). "The cooperation of IL-10 production by macrophages and CD4+ T cells was associated with reduce morbidity to experimental schistosomiasis." (PMID 32922381, 2020). "The cytokine levels of TNF-α, IFN-γ, IL-6, IL-4, IL-5, IL-10, IL-13, and IL-17A in the sera of acute phase schistosomiasis were all significantly increased in the IUT and VEH groups compared with the UI group." (PMID 30258438, 2018). "Studies of murine schistosomiasis demonstrated that resistance to reinfection after a drug-abbreviated infection was improved in the context of anti-IL-10 treatment." (PMID 28871261, 2017). "Specific cytokines, in particular IL-2, IL-4, IL-5, IL-10, and IFN-ɤ have been implicated in regulation of granulomatous response on schistosomiasis." (PMID 27378927, 2016). "For example, IL-10 production (an important anti-inflammatory cytokine) expressed at low levels in human schistosomiasis requires the phosphorylation of p38 MAPK." (PMID 25885182, 2015). "This is of major importance as studies of human schistosomiasis indicate the importance of IL-10 in regulating morbidity, and IL-10 has been shown to inhibit the development of protective immunity to secondary schistosome infection." (PMID 26191954, 2015). "It was previously reported that IgG1 and IL-10-mediated immune responses downregulate the granulomatous hypersensitivity reaction of schistosomiasis." (PMID 25887456, 2015). "Several studies have demonstrated that IL-10 is involved in down-modulating pathological inflammatory responses in schistosomiasis." (PMID 25223302, 2014). "In a murine model of schistosomiasis, it was shown that IL-10 played a significant role in reducing immunopathology, especially in the chronic stage of an infection." (PMID 25372668, 2014).
schistosomiasis (continued). "IL-6 has been demonstrated to have an anti-inflammatory role in schistosomiasis, down-regulating TH-1 responses by inducing the expression of IL-10 which in turn down-regulates expression of INF-γ." (PMID 23840855, 2013). "rSjGALE immunization also induced high levels of IL-10, which were found to be regulatory cytokines in many studies and its production is also important in protecting mice against murine schistosomiasis and in the regulation of the granulomatous process." (PMID 22848700, 2012). "Evidence from human lymphatic filariasis, onchocerciasis and schistosomiasis records a down-modulation of immunity which is consistent with the activity of Treg-like cells, involving IL-10, TGF-β and CTLA-4 1, 46–49." (PMID 17563918, 2007). "Taken together these results support the proposition that in schistosomiasis at least, IL-10 is acting as a regulatory cytokine which inhibits a protective IL-5 dependent response." (PMID 18045464, 2007). "Collectively, our findings suggest a novel therapeutic strategy for schistosomiasis: PKCλ/ι-targeted modulation of IL-10 signaling could represent a precision approach to simultaneously sustain antiparasitic immunity while curbing fibrosis progression." (PMID 41154658, 2025). "Furthermore, the attenuation of traditional markers such as eosinophilia and IL-10 in multivariate analysis highlights the complex interplay between immune effectors and regulatory pathways in schistosomiasis." (PMID 40526709, 2025). "Previous reports suggest that in schistosomiasis, B10 cells may mitigate egg-induced liver tissue damage and fibrosis through the secretion of IL-10." (PMID 41154658, 2025). "In schistosomiasis, IL-10 is often elevated during chronic stages to counterbalance pro-inflammatory responses, but this increase may not always correlate directly with infection status when controlling for confounders." (PMID 40526709, 2025). "IL-4 and IL-10 have well-established and complementary roles in schistosomiasis immunobiology." (PMID 40526709, 2025). "The lack of a significant association between IL-10 levels and schistosomiasis in our multivariate analysis, despite significance in univariate analysis, needs careful consideration." (PMID 40526709, 2025). "In addition, IL-10 plays an important role in the modulation of cytokine networks in schistosomiasis." (PMID 33996977, 2021). "The production of IFN-γ depends on the relative concentration of IL-10, hence it is thought that IL-10 may be functionally important in the development of morbidity in schistosomiasis and disease progression." (PMID 34239575, 2021). "We therefore hypothesised that the IL-10 -1082 A allele and TNF-α 308 A allele, as well as genotypes with these alleles, would be associated with reduced susceptibility to schistosomiasis in our study population." (PMID 34485462, 2020). "The Th1 response during the early stage of schistosomiasis is downregulated by IL-4 and IL-10." (PMID 32132991, 2020). "Thus, IL-10 acts as an important regulator to prevent excessive Th1 and Th2 responses during the development of schistosomiasis." (PMID 32132991, 2020). "However, the current knowledge of B cell subsets differentiation and IL-10-independent immunoregulatory mechanisms of B cells in schistosomiasis is insufficient." (PMID 32197642, 2020). "IL-10 plays a protective immunomodulatory role during schistosomiasis." (PMID 31194740, 2019). "A possible explanation for this was that people might be in the early stage of infection with S. japonicum or taking praziquantel for the treatment of schistosomiasis that could impact the levels of IL-10 and IFN-γ in plasma." (PMID 30057918, 2018). "In addition, the anti-inflammatory cytokine, IL-10, plays a central regulatory role in the pathogenesis of schistosomiasis, and the maintenance of IL-10 expression during acute and chronic schistosome infection is critical for host survival." (PMID 30589840, 2018).
schistosomiasis (continued). "According McManus and Loukan (2008), IL10 is of fundamental importance in the generation of the conditions for the host protective homeostatic functions in schistosomiasis and the CD4CD25 T cells have been identified as the main source of IL-10 in mice infected by Schistosoma mansoni." (PMID 27378927, 2016). "In this context, IL-10 was reported to be related to the intensity of human schistosomiasis, which may be the cumulative result of repeated exposure to infectious cercariae as well as eggs released by adult worms." (PMID 25624353, 2015). "The expression of IL-12, IL-10, and IL-10R was evaluated in monocytes of schistosomiasis patients." (PMID 24757288, 2014). "And blockage of IL-10 in the in vitro granuloma assay lead to a significant increase in granuloma size with cells from intestinal patients but not with individuals in the acute phase or with the hepatosplenic form of schistosomiasis." (PMID 23349889, 2013). "CD25+cell depletion combined with the inhibition of IL-10 may represent a promisingnew approach for effective schistosomiasis vaccine design." (PMID 22802961, 2012). "Apart from IL-10, the levels of response observed in cord blood were much lower than those that were found among the mothers during pregnancy, or reported in infected children and adults living in schistosomiasis endemic areas." (PMID 21888656, 2011). "Enhanced production of IL-10 by lymphocytes stimulated with parasite antigen has been associated with reduced skin test responses in children infected with schistosomiasis, but not geohelminth infections." (PMID 21039971, 2010). "Thus, IL-10 could reduce the acute pathology of schistosomiasis, regulating the immune response and controlling the chronic morbidity in patients." (PMID 27378927, 2016). "Sm16/SPO-1 has been implicated in inducing the anti-inflammatory cytokine, IL-10 and thus involved in host immunomodulation, while, as its name suggests, FABP/Sm14 plays an important role in the binding and transport of lipids and is being developed as a schistosomiasis vaccine candidate." (PMID 27467385, 2016). "Indeed, whole-blood cultures from infected individuals from an area in northern Senegal where schistosomiasis is endemic secrete larger quantities of regulatory interleukin-10 (IL-10) in response to cercarial E/S material than do those from uninfected individuals." (PMID 25624353, 2015). "Analysis of the peripheral blood mononuclear cells from the population will allow us to determine whether in human schistosomiasis, as recently reported in filariasis, the majority of IL-10 production derives from CD25-negative Th2-like cells, rather than the regulatory T cell subset." (PMID 21039611, 2010). "In another flatworm infection, schistosomiasis, CD9 has recently been identified as a key surface marker for murine IL-10+ CD19+ Bregs involved in infection progression." (PMID 40725240, 2025). "The study sought to evaluate cytokine (IL-2, IL-4, IL-5, IL-10, TNF, and IFN-γ) profiles in the serum of children infected with schistosomiasis before and after treatment with praziquantel (PZQ)." (PMID 34239575, 2021). "Cytokines, such as IL-4, IL-10, IFN-γ, IL-17, and IL-9, have been reported to be key signals in the immune cells involved in schistosomiasis." (PMID 33628844, 2021). "For example, circulating cytokines interleukin-10 (IL-10) and tumor necrosis factor (TNF) are two biomarkers that have consistently been shown as elevated in human schistosomiasis." (PMID 30453907, 2018). "In examining other immune indicators and responses we noted that whole blood cultures from those individuals with schistosomiasis produced similar levels of IL-5, IFN-γ and IL-10 as compared to our uninfected controls after stimulation with HbSAg." (PMID 27926921, 2016).
schistosomiasis (continued). "The production of IL-10 during this latter period seems to have an important role in hepatic granuloma formation and in the regulation of CD4+ T cell responses in schistosomiasis, as well as in the transition from acute to chronic disease state." (PMID 26191954, 2015). "Indeed, cercarial E/S antigens specifically promote production of regulatory IL-10 by antigen presenting cells (Sanin & Mountford, manuscript in preparation), and by cultures of whole blood cells obtained from infected individuals from endemic areas for schistosomiasis." (PMID 25974019, 2015). "Its expression change trend was similar as IL-10 mRNA expression in mouse livers with schistosomiasis (Data not published)." (PMID 40895302, 2025). "A previous study in an area highly endemic for S. haematobium suggested that urinary IL-6 and IL-10 have this potential but not much is known in relation to urinary cytokines and the influential factors in schistosomiasis." (PMID 37018184, 2023). "Furthermore, AAMs produce IL-10 and TGF-β, cytokines that promote healing and tissue repair during schistosomiasis." (PMID 36263057, 2022). "In human schistosomiasis, S. mansoni and S. haematobium up-regulate IL-1ra, IL-10, and TNF-α, whereas S. japonicum induces the up-regulation of several cytokines, including IL-1β, IL-1ra, IL-2, IL-6, IL-8, IL-10, IL-15, IL-18, and TNF-α." (PMID 36339337, 2022). "A study in mice showed that IL-10 is an important immunoregulatory cytokine in acute schistosomiasis, but it plays no essential role in the process of immune downmodulation in chronic S. mansoni infection in mice." (PMID 34970264, 2021). "It has been reported that IL-10, secreted from iTregs and Th2 cells, inhibits IL-12 production by CD40 agonist-stimulated DC and iTregs, thus suppressing development of egg-specific Th1 responses during schistosomiasis." (PMID 32132991, 2020). "Eosinophil counts correlated with levels of both cytokines (r = 0.53, p = 0.001 and r = 0.38, p = 0.019, for IL-10 and TNF, respectively); the association of eosinophilia with schistosomiasis was not significant (OR = 2.538, p = 0.282)." (PMID 30453907, 2018). "However, during the chronic phase of schistosomiasis, the levels of TNF-α, IFN-γ, IL-6, IL-4, IL-10, and IL-17A remained increased in the IUT and VEH groups." (PMID 30258438, 2018). "In the Mentha-15 experimental group there was no reduction in the IL-10 anti-inflammatory cytokine expression in this schistosomiasis model when compared to the positive control group." (PMID 27378927, 2016). "IL-10 and TGF-β were both induced and both recognized as factors can promote host survival by suppressing pro-inflammatory cytokine production and ova-induced hepatotoxicity in the acute phase of schistosomiasis." (PMID 23152879, 2012). "This may suggest that IL-10 production in schistosomiasis is secondary to other immune processes rather than being an independent determinant of infection status." (PMID 40526709, 2025). "As little is known about the suppressive effect of Treg cells and IL‐10 in Ascariasis, which may not necessarily function in the same manner as in Schistosomiasis, we should verify the contribution of these cells to wheezing in the future studies." (PMID 31256445, 2019). "IL-6 can up-regulate IL-10 production upon exposure to S. mansoni eggs in vivo and the two cytokines together negatively regulate IL-12 and IFN-γ production during the early phase of infection, indicating an anti-inflammatory role of IL-6 during schistosomiasis." (PMID 27152725, 2016). "However, no children with the IL-10-819 TT genotype had schistosomiasis." (PMID 34007813, 2021).